ANKS1B (ankyrin repeat and sterile alpha motif domain containing 1B)
Description:
Isoform 2 may participate in the regulation of nucleoplasmic coilin protein interactions in neuronal and transformed cells. Isoform 3 can regulate global protein synthesis by altering nucleolar numbers. Isoform 4 may play a role as a modulator of APP processing. Overexpression can down-regulate APP processing.
Synonyms: AIDA-1; EB-1; cajalin-2; ANKS2; AIDA; EB1
Tractability: Antibody: its Gene Ontology location is reachable by antibodies, with high confidence. PROTAC: ubiquitination databases record sites on it; its protein half-life has been measured.
Safety:
Unwanted effects reported when the protein is acted on. In parentheses: how it was acted on, where the effect was seen, and who reports it.
alcohol dependence (source: ClinPGx)
heroin dependence (source: ClinPGx)
methamphetamine dependence (source: ClinPGx)
Gene: Protein-coding gene on chromosome 12 (98,726,457 to 99,984,936, reverse strand). Ensembl gene ENSG00000185046.
Subcellular location: Cytoplasm; Nucleus (Isoform 2); Postsynaptic density (Isoform 3); Cell projection, dendritic spine; Nucleus; Nucleus, Cajal body; Nucleus (Isoform 4); Nucleus (Isoform 6)
Subcellular location (Human Protein Atlas): Nucleoplasm; Plasma membrane
Gene Ontology:
Molecular function: ephrin receptor binding
Biological process: ephrin receptor signaling pathway; regulation of synaptic plasticity by receptor localization to synapse
Cellular component: nucleoplasm; glutamatergic synapse; presynaptic cytosol; Cajal body; cytoplasm; dendritic spine; nucleus; postsynaptic density
Genetic constraint (gnomAD): Loss-of-function variants: 27 observed, 125.01 expected, observed/expected ratio (o/e) 0.22, 90% interval 0.16 to 0.3. The upper end of that interval is the gene's LOEUF score, 0.3, which puts it in group 1 of 6, group 1 being the genes least tolerant of losing a copy. Missense variants: 1,086 observed, 1,484.5 expected, observed/expected ratio (o/e) 0.73, 90% interval 0.69 to 0.77. Synonymous variants: 516 observed, 546.69 expected, observed/expected ratio (o/e) 0.94, 90% interval 0.88 to 1.01.
Homologues: Orthologues: chimpanzee ANKS1B (96% identical), pig ANKS1B (96% identical), macaque ANKS1B (95% identical), guinea pig ANKS1B (94% identical), rat Anks1b (93% identical), mouse Anks1b (93% identical), rabbit ANKS1B (92% identical), zebrafish anks1b (65% identical), dog ANKS1B (38% identical), tropical clawed frog anks1b (18% identical). Paralogues in human: ANKS1A (45% identical).
Diseases named in the same sentence as ANKS1B in open-access papers:
ANKS1B is named in the same sentence as 37 diseases in open-access papers, as found by Europe PMC text mining. Sharing a sentence is not in itself a finding about the gene and the disease. The quoted sentences say what the papers report.
autism (7 papers, 2011 to 2024). Persistent deficits in social interaction and communication and interaction as well as a markedly restricted repertoire of activity and interest as well as repetitive patterns of behavior. "We recently characterized ANKS1B haploinsufficiency, a new genetic syndrome presenting with autism and other neurodevelopmental disorders that is caused by a monogenic deletion in the ANKS1B gene." (PMID 37255534, 2023). "Here we describe individuals with monogenic heterozygous microdeletions in ANKS1B, a predicted risk gene for autism and neuropsychiatric diseases." (PMID 31388001, 2019). "In this study, we discovered that microdeletions in the ANKS1B gene encoding AIDA-1 lead to a neurodevelopmental syndrome characterized by autism, ADHD, and speech and motor impairment." (PMID 31388001, 2019). "We identified ANKS1B as a crucial gene for human development in which rare loss-of-function variants cause neurodevelopmental disorders, including autism, ADHD, and deficits in speech and motor function." (PMID 31388001, 2019). "Mouse models with heterozygous deletions in the ANKS1B gene have shown a number of distinctive behavioural signs typical of autism." (PMID 38674362, 2024). "Surprisingly, only Olig2-Cre driven Anks1b conditional mutant mice had social deficits, suggesting a significant contribution of oligodendrocyte dysfunction to autism-like features in ANDS." (PMID 38129387, 2023). "ANKS1B encodes the CASK-interacting adaptor protein, functional in autism and neuropsychiatric diseases." (PMID 37760363, 2023). "We identified two families (EIN-1 and EIN-2) harboring monogenic microdeletions in ANKS1B who had been referred for medical genetic evaluation due to various neurodevelopmental disorders, including autism, ADHD, speech apraxia, and motor delays." (PMID 31388001, 2019).
breast carcinoma (7 papers, 2012 to 2024). "Of the network genes ESR2, STRN and ANKS1B exhibited recurrent disrupting alleles among cancer cases, emphasizing their potential role in breast cancer predisposition." (PMID 22737080, 2012). "Among these, 11 CNVRs overlapped with 12 genes (GSTM2, RAB40B, HLA_DRB5, HLA_DRB6, EYA1, DOCK3, ANKS1B, CACNA1C, RAB11FIP3, BAGE, SGCZ, POM121c) and were specifically associated with breast cancer risk and OS." (PMID 29116104, 2017). "Due to its high stability, circRNA is an excellent biomarker for human diseases, especially cancer; examples include circ-SMARCA5 as a biomarker for hepatocellular carcinoma, circ-ANKS1B for breast cancer, circ-UBXN7 for bladder cancer and circ-LMTK2 for gastric cancer." (PMID 31631067, 2019). "Besides, circ-ANKS1B was reported to be significantly upregulated in triple-negative breast cancer, and it was a high risk predictor of breast cancer metastasis." (PMID 33222697, 2020). "rs2373011 is located in the intron region of the ANKS1B gene, whereas rs2229165 of the CSF1 gene has also been suggested to be involved in breast cancer etiology." (PMID 39194753, 2024). "The results showed that the migratory and invasive capabilities were dramatically reduced only in si-both, but not si-ANKS1B transfected breast cancer cells, suggesting that circANKS1B, but not linear ANKS1B, is crucial for breast cancer migration and invasion." (PMID 30454010, 2018).
Alzheimer disease (5 papers, 2011 to 2023). A progressive, neurodegenerative disease characterized by loss of function and death of nerve cells in several areas of the brain leading to loss of cognitive function such as memory and language. "ANKS1B (rs7132513) encodes a protein predominantly expressed in the brain and testis, which interacts with amyloid beta protein precursor, and may play a role in normal neurodevelopment as well as the pathogenesis of Alzheimer's disease." (PMID 37337823, 2023). "ANKS1B, the homolog of CG4393, interacts with amyloid beta protein precursor, which has been implicated in the pathogenesis of Alzheimer's disease." (PMID 22715409, 2012). "ANKS1B is a multi-domain protein that has a role in the pathogenesis of Alzheimer’s disease." (PMID 37513116, 2023).
lung carcinoma (4 papers, 2014 to 2024). "A systemic search for SNPs in apoptotic-pathway genes revealed a relationship between the SNPs of ANKS1B and lung cancer risk in humans, but their roles in lung cancer development are largely unknown." (PMID 37513116, 2023). "What remains unclear is whether these SNPs are also found in lung cancer tissues and whether they are functionally associated with expression or activity of the ANKS1B protein." (PMID 24479813, 2014). "Also, for PHACTR1 and ANKS1B potential roles in lung cancer have been described before." (PMID 33953302, 2021). "Although the specific role of circ-Anks1b in rodent lungs has not been studied, the strong detection of the protein in epithelial cells at Year 2 is suggestive of a role for this gene in the onset of lung cancer development in rats." (PMID 37513116, 2023).
alcoholism (3 papers, 2022 to 2026). "Our prior genome-wide association study (GWAS) identified ANKS1B as a significant shared genetic risk factor for heroin, methamphetamine, and alcohol dependence, suggesting a broad role in addiction vulnerability." (PMID 42228033, 2026). "In addition, in a study with people of Chinese Han ethnicity, ANKS1B has been associated with alcoholism." (PMID 37170185, 2023). "In addition, in a study with people of Chinese Han ethnicity, ANKS1B has been found to be associated with alcoholism." (PMID 36371147, 2022).
schizophrenia (3 papers, 2011 to 2022). A major psychotic disorder characterized by abnormalities in the perception or expression of reality. "In the network, candidate genes with nominal significance such as ANKS1B, CNTN2, CNTNAP2, GABBR2, NCOR2, and NTRK3 also may be involved in the pathology of schizophrenia." (PMID 30323833, 2018).
triple-negative breast carcinoma (2 papers, 2020 to 2023). An invasive breast carcinoma which is negative for expression of estrogen receptor (ER), progesterone receptor (PR), and human epidermal growth factor receptor 2 (HER2). "The circular RNA of Anks1b promotes metastasis of triple-negative breast carcinoma by modulating epithelial-to-mesenchymal transition." (PMID 37513116, 2023).
attention deficit-hyperactivity disorder (1 paper, 2023). A disorder characterized by a marked pattern of inattention and/or hyperactivity-impulsivity that is inconsistent with developmental level and clearly interferes with functioning in at least two settings (e.g. at home and at school). "Heterozygous deletions in the ANKS1B gene cause ANKS1B neurodevelopmental syndrome (ANDS), a rare genetic disease characterized by autism spectrum disorder (ASD), attention deficit/hyperactivity disorder, and speech and motor deficits." (PMID 38129387, 2023).
B cell acute lymphocytic leukaemia (1 paper, 2011). "We found loss at ANKS1B, while overexpression of ANKS1B is reported in pre-B cell acute lymphocytic leukaemia." (PMID 21235737, 2011).
cocaine addiction (1 paper, 2026). "However, the specific function of ANKS1B in cocaine addiction and its associated neural mechanisms were unknown." (PMID 42228033, 2026).
exfoliation syndrome (1 paper, 2021). An autosomal dominant disorder caused by mutations in the LOXL1 gene, encoding lysyl oxidase homolog 1. "Linkage disequilibrium and epistasis analysis for this variant identified the genes LHFPL3, GALNT6, PIH1D1, ANKS1B, and METRNL as potentially involved in the etiopathogenesis of exfoliation syndrome and glaucoma, which were not previously associated with the disease." (PMID 34440405, 2021).
glaucoma (1 paper, 2021). Increased pressure in the eyeball due to obstruction of the outflow of aqueous humor. "In our study, the newly identified linked genes LHFPL3, GALNT6, PIH1D1, ANKS1B, and METRNL may be involved in the etiopathogenesis of XFS and glaucoma." (PMID 34440405, 2021).
kidney tumor (1 paper, 2024). "Compared with the patient-matched normal kidney tissue, ANKS1B is expressed at a decreased level in the kidney tumor tissue of RCC patients." (PMID 38957811, 2024).
tuberous sclerosis (1 paper, 2023). Hereditary disease characterized by seizures, intellectual disability, developmental delay, and skin and ocular lesions. "Indeed, most (if not all) identified ASD mouse models such as those for Fragile X, tuberous sclerosis, Angelman Phelan McDermid, and ANKS1B syndromes show deficits in diverse forms of synaptic function as well as altered neuronal and synaptic morphology." (PMID 37255534, 2023).
neurodevelopmental disorder (5 papers, 2017 to 2024). A behavioral and cognitive disorder with onset during the developmental period that involves impaired or aberrant development of intellectual, motor, or social functions. "Since the Nestin-Het model essentially reproduces a heterozygous Anks1b microdeletion on an isogenic background, our results strengthen the causal link between ANKS1B deletion and neurodevelopmental disorders in probands." (PMID 31388001, 2019). "Probands with ANKS1B microdeletions exhibit neurodevelopmental disorders in childhood, suggesting dysregulation of early neural development." (PMID 31388001, 2019). "Similarities between the neurodevelopmental disorders in these individuals and those with monogenic ANKS1B deletions suggests that ANKS1B haploinsufficiency contributes to clinical presentation in these patients." (PMID 31388001, 2019). "In two patients we detected de-novo CNVs encompassing genes previously associated with different neurodevelopmental disorders (NRXN1, ANKS1B, UHRF1BP1)." (PMID 29179725, 2017). "Anks1b is a crucial gene for human development, in which loss-of-function variants lead to the reduced synaptic expression of the NMDAR subunit GluN2B, impaired NMDA-dependent LTP and LTD, and neurodevelopmental disorders." (PMID 34988919, 2022). "From the identity of individual molecules to their predicted roles in disease, our analysis of the AIDA-1 interactome predicts participation of ANKS1B in cellular processes crucial to normal development and implicated in the etiology of neurodevelopmental disorders." (PMID 31388001, 2019). "In addition, a 190 kb deletion encompassing the ANKS1B gene was reported in a patient with EO-OCD, enhancing the possible role of the gene in neurodevelopmental disorders." (PMID 29179725, 2017). "By generating neurons from patients with ANKS1B haploinsufficiency syndrome and the Anks1b Nestin-Het mouse model, we have developed tools to further probe the mechanisms by which AIDA-1 enables normal brain development and ANKS1B haploinsufficiency contributes to neurodevelopmental disorders." (PMID 31388001, 2019).
cancer (4 papers, 2012 to 2023). A tumor composed of atypical neoplastic, often pleomorphic cells that invade other tissues. "Dysregulation of its expression was found in smoking-related clear cell renal cell carcinoma, and a few single nucleotide polymorphisms in ANKS1B have been associated with cancers." (PMID 37296980, 2023). "Intriguingly, several studies identified the pro-cancer roles of the circular RNA of ANKS1B (cANKS1B), which is a circular RNA originating from exon 5–8 of the ANK1B gene." (PMID 37296980, 2023). "ANKS1B is involved in apoptosis and thus has the potential to play a key role in cancer development." (PMID 24479813, 2014). "That notwithstanding, these results from another smoking-related cancer further suggest a possible role for ANKS1B to be a smoking-related molecular alteration in cancer and underscore the potential for these results to advance the knowledge of ccRCC etiology and prevention." (PMID 24479813, 2014).
neurologic disease (3 papers, 2015 to 2021). "Consistent with clinical findings in ANKS1B haploinsufficiency syndrome, Neurological Disease and Developmental Disorder were among the top hits in the category of Diseases and Disorders." (PMID 31388001, 2019). "The downregulated genes include one encoding a protein that interacts with amyloid-β precursor protein (ANKS1B) and two encoding glutamate receptors (GRIA2, GRM3), suggesting changes in astrocytic responses to synaptic glutamate release in multiple neurological disorders." (PMID 34172753, 2021). "SAFB1 mediated isoform-specific changes in ANK3, ANKS1B, SAP97 (DLG1), ADD2, KIF16B, and ELK3, as well as in genes linked to the cytoskeleton and/or synaptic function and the aetiology of neurologic disease." (PMID 26694817, 2015).
tumor (3 papers, 2014 to 2024). "Here, we showed that ANKS1B is under expressed in ccRCC tumor tissue in comparison to patient-matched normal." (PMID 24479813, 2014). "Thus, ANKS1B expression in smokers is down regulated in the tumor tissue in comparison to the patient-matched normal kidney tissue and this down regulation is potentially a key event that supports ccRCC development." (PMID 24479813, 2014). "Specifically, in stage 1 (non-obese cohort) ANKS1B had a tissue type-by-smoking status interaction p-value of 0.0008; the fold change of expression between smokers and non-smokers was 1.08 (p = 0.02) in normal tissues and 0.92 (p = 0.01) in tumor tissues." (PMID 24479813, 2014). "From our observational data, we show that ANKS1B is up regulated in smokers relative to non-smokers in normal kidney tissue; however, it is down regulated in smokers relative to non-smokers in ccRCC tumor tissue." (PMID 24479813, 2014). "In normal kidney tissue ANKS1B, ACOT6, EYS, CHRNA6, MT1G and UTY were up regulated in smokers in comparison to non-smokers; however, these genes tended to be down regulated in smokers versus non-smokers in ccRCC tumor tissue." (PMID 24479813, 2014).
genetic disease (2 papers, 2019 to 2023). "Our findings formalize a link between the synaptic protein AIDA-1 and a rare, previously undefined genetic disease we term ANKS1B haploinsufficiency syndrome." (PMID 31388001, 2019).
ANKS1B also shares sentences with these, for which no sentence is quoted: bladder cancer (2 papers); gastric cancer (2); hepatocellular carcinoma (2); autism spectrum disorder (1); bipolar disorder (1); clear cell renal cell carcinoma (1); cognitive deficits (1); cortical dysplasia-focal epilepsy syndrome (1); diabetes (1); diarrhoea (1); fragile X syndrome (1); Hypertension (1); metabolic syndrome (1); myeloid leukemia (1); Obesity (1); Parkinson disease (1); Speech apraxia (1); Tics (1).